IFNG (interferon gamma)
Diseases named in the same sentence as IFNG in open-access papers (continued):
Sharing a sentence is not in itself a finding about the gene and the disease.
tumor (continued). "In solid tumors, interferon-gamma (IFN-γ)-producing Tc1 cells are the most frequently observed subtype, but different tumor types harbor different CTL subtypes." (PMID 35326515, 2022). "Of note, the deconvoluted tumor epithelial cells of SCLC-I tumors showed up-regulation of genes with immune-related functions such as allograft rejection and the interferon-gamma response." (PMID 36428693, 2022). "Altogether, these data show that TAMs capture and present tumor antigens to CD4 T cells at the tumor site, inducing IFNγ production by antigen specific effector T cells." (PMID 35903540, 2022). "Recent studies have begun to dissect the mechanistic relationship between the integrity of the IFNγ signaling pathway and ICB resistance in the tumor microenvironment." (PMID 34385592, 2022). "Tumor glycolysis can drive lactic acid buildup in the TME, and 15 mM lactic acid treatment of NK cells ex vivo has been shown to completely abolish IFNγ production." (PMID 35414042, 2022). "For further confirmation of our TME flow cytometry data showing CD4 and CD8 T-cell activation, we found an increase in Th1 pro-inflammatory cytokine (IFNγ, TNFα, IL-2, and KC/GRO) levels in the tumor lysate." (PMID 35651802, 2022). "Analysis of the tumor immune infiltrate showed that DMXAA monotherapy up-regulated production of anti-tumor cytokines (i.e., IFNγ, Granzyme B, and TNFα) in both CD8+ and CD4+ T cells, which was further enhanced by combining with olaparib therapy." (PMID 35641483, 2022). "Although there were variations in IFNγ levels across TIL cultures within the same subtype, overall, IFNγ levels upon general stimulation were similar across TILs derived from MFS, UPS, OS, and LMS tumour specimens." (PMID 35158816, 2022). "Among them, CD8+ T cells infiltrate tumors as a symbol of immune recognition and destroy tumor cells by secreting granzyme B, TNF, and IFNγ, indicating better survival in OC patients." (PMID 35837397, 2022). "Intratumoral analysis showed that tumor areas with high levels of hypoxia, as indicated by staining of HIF1α, displayed markedly reduced CD8+ T cell infiltration as well as IFNγ expression compared to low hypoxic areas." (PMID 35840558, 2022). "While IL-23 inhibits ferroptotic host cell death, some cytokines, such as IFNγ, drive ferroptosis via STAT1 signaling in tumor cells." (PMID 36138043, 2022). "IFNγ is present in the blood of CLL patients and is also found in the tumor microenvironment, where it can activate CLL cells in both paracrine and autocrine manners." (PMID 36209148, 2022). "Animal experiments have shown that tumor-derived factors such as IL-6, CXCL16, IFNγ, TNFα, and IGFBP-3 positively regulate the expression of CD38, and high expression of CD38 can enhance the immunosuppressive and tumor-promoting capacity of MDSCs." (PMID 36119033, 2022). "Stimulated CD4+ T helper 1 cells secrete the effector cytokines interferon-gamma (IFN-γ) and tumor necrosis factor alpha (TNF), which induce senescence in tumor cells." (PMID 35563820, 2022). "Using IFNγ, PMA/ionomycin, and sCD40L we mimicked the clonal stimulation that occurs in the tumor microenvironment of CLL cells." (PMID 36209148, 2022). "Two effector CD4+ T cells, characterized by high expression of either IFNγ and TNF or GZMA and GZMK, showed an anti‐tumour function." (PMID 35184398, 2022). "To further investigate changes in the tumor microenvironment, we determined the levels of TAM‐produced cyto/chemokines Ccl2, Ifnγ, Cxcl10, Cxcl9, Csf1, Csf3, and Il‐6 in the peritoneal lavage." (PMID 36221913, 2022). "Bulk RNA-seq analysis of sorted tumour-infiltrating CD8+ T cells revealed higher expression of IFNG, GZMB and PRF1 in post-treatment samples, indicating enhanced cytotoxic potential of tumour-infiltrating CD8+ T cells following PI3Kδi treatment." (PMID 35508656, 2022). "The IFNγ signaling pathway, which functions through JAK-STAT signaling, has dual effects on anti-tumor immunity." (PMID 36142818, 2022).
tumor (continued). "Remarkably, enrichment analysis revealed that Uba6-null tumour cells had a marked increase in gene expression profiles evoked by inflammatory cytokines, such as TNF-α, IFNα, and IFNγ." (PMID 36109526, 2022). "Moreover, the proportions of interferon γ (IFNγ) and granzyme B (GzmB)-producing CD8+ T cells were significantly increased in KO mice than that in WT mice, suggesting that compared with WT mice, the anti-tumor immunity was enhanced in the FcγRIIB deficient mice." (PMID 34976216, 2022). "The biological activity of GEN1046 on T cells was reflected by increases in IFNγ, TNFα, IL2, and CXCL10 in peripheral blood in MC38-hPD-L1 and MC38-WT tumor–bearing mice." (PMID 35176764, 2022). "We found that in MDS tumor cells the upregulation of PD-L1 is contributed by both the unfolded protein response (UPR) and to a lesser extent by IFNγ." (PMID 35992887, 2022). "For example, IFNγ induces the expression of immune inhibitory molecules, including B7-H1 (PD-L1), indoleamine 2,3-dioxygenase (IDO), and arginase, in the tumor microenvironment." (PMID 34385592, 2022). "At the same time, the T cells secrete pro-inflammatory cytokines, such as interferon-gamma (IFN-γ) and tumor necrosis factor alpha (TNF), which can have direct cytotoxic activity on tumor cells, as well as promoting further anti-tumor immune activity." (PMID 35874669, 2022). "Following 72 h exposure, we observed the induction of several antigen presentation genes, with IFNγ inducing a greater change than the type I interferons, and a dramatic increase of MHC-I protein on the cell surfaces of the MTB/TOM tumor cells." (PMID 35760778, 2022). "Lactate was found to inhibit nuclear factor of activated T cells (NFAT), leading to the inactivation of tumor-infiltrating CD8+ T cells and NK cells and reduced IFNγ production." (PMID 36050306, 2022). "More importantly, A20 enhancer activation abrogated the difference in tumor growth between mice bearing WT and Arid1a KO cells, and MDSCs, CD8+ T cells and IFNγ+ expressing CD8+ T cells were present in similar proportions." (PMID 36435834, 2022). "This view relates to the CAF secretome containing factors such as IL-10, TGFβ, IFNγ and IL-6 that are known to recruit macrophages, natural killer cells and CD3+ T lymphocytes during tumor initiation to promote an anti-tumor immune response." (PMID 36671452, 2022). "Several studies have reported that treatment with ICIs increased the production of IFNγ in the TME, which enhanced tumor regression." (PMID 35053427, 2022). "The suppressive effects of tumor-treated Cd36−/− BMDMs on CD8+ T cells were reduced when compared with WT BMDMs, as demonstrated by increased GzmB and IFNγ expression of CD8+ T cells." (PMID 36184646, 2022). "Interferon-gamma (IFN-γ) and IL-10 are cytokines that can control the immune and inflammatory environment, thus acting as anti-tumor molecules." (PMID 35765486, 2022). "We next used cytokine bead arrays to examine the secretion of TNF and IFNγ by sgNkg7 and sgNT OT-I T cells during synapse with MC38-OVA tumor targets, as these are key cytokines that contribute to the anti-tumor effector activity of CD8+ T cells." (PMID 35874669, 2022). "In particular, six tumor cytotoxicity-related molecules (GZMA, GZMB, GZMH, IFNG, FASLG, and NKG7) from T cells had significantly higher levels in the BM than in PB." (PMID 40977909, 2022). "For example, utilizing a CRISPR/Cas9 approach to disrupt A2AR on CAR-T cells in culture led to an increase in IFNγ, TNFα, JAK/STAT pathway genes, CAR-T cell survival, and control of tumor burden in a murine breast cancer model." (PMID 35039633, 2022). "Among them, we paid special attention to multiple immune pathways, including the inflammatory response, interferon gamma response, TNF-a signaling pathway and IL-6/JAK/STAT3 signaling, all of which had been shown to be closely related to tumor development." (PMID 35991547, 2022).
tumor (continued). "DC-SIGN engagement by sialyl-Lewis motifs activates and enhances the maturation of DCs leading to the enrichment of antigen-specific IFNγ production and CTL response, and the suppression of tumor growth in mice." (PMID 36353633, 2022). "IL12, produced by tumour antigen activated APCs, and IL2 are major drivers of the Th‐1 response, IFNG is a major effector and CTLs and macrophages the effector cells." (PMID 35445563, 2022). "We finally showed that non-responders to anti-PD-1 and/or anti-CTLA-4 ICI therapies have lower IFNG, Merck18, CD274 and CD8 scores, and lower dysfunction of the tumor." (PMID 36389735, 2022). "The combination with a GM-CSF tumor vaccine in preclinical models also had shown activation of DCs and anti-tumor specific CD8+ IFNγ+ T cells." (PMID 36230990, 2022). "Concordantly, peripheral and tumor infiltrated CD8+T cells, as well as GMZB+CD8T and IFNγ+CD8T were increased by HB3089 treatment, suggesting the activation of antitumor immunity." (PMID 36513640, 2022). "Interestingly, this ubiquitination-mediated control of IFNγ signaling at the level of IFNγ-R1 may constitute a more common mechanism, since recently another ubiquitin ligase, FBXW7, was implicated in governing IFNγ-R1 signaling in breast cancer." (PMID 35395848, 2022). "The mutated Fc-domain can induce activation of NK cells more potently, which mounts robust inflammatory responses including production of IFNγ, TNFα, and IL6 secreted from NK cells to further enhance immune reaction in tumor microenvironment." (PMID 36922936, 2022). "In NMIBC, T1 tumours (combined from Northwestern Memorial Hospital (NMH) and UROMOL2021) were split by the IFNγ-signature into high and low groups, with tumour recurrence being 50% more likely in patients in the IFNγ-signaturelow group." (PMID 36358715, 2022). "It has been previously demonstrated that there is an interplay between T cells and tumor vascularization inducing CD4+ T-cell activation, IFNγ production, and subsequent boosting angiogenesis homeostasis, but also immune response." (PMID 36294987, 2022). "Tumor suppressive activity of Vγ2+ T cells was dependent on both TCR and NKG2D signals, which regulated their production of IFNγ." (PMID 35480230, 2022). "Subsequently, the activated NK cells release perforin and granzymes or produce cytokines, such as interferon-gamma (IFN-γ), to kill the tumor cells." (PMID 36186137, 2022). "Significant increases in IFNG, IL‐18, IL‐1β, IL‐8, TNF‐α, TLR4, MyD88, and NF‐κB levels were found in the P. copri and tumour control groups." (PMID 35735103, 2022). "Interferon gamma (IFN-γ) secreted by CD8+ T cells downregulates the expression of SLC3A2 and SLC7A11 in tumour cells, impairs the uptake of cystine and, as a consequence, promotes lipid peroxidation and ferroptosis in tumour cells." (PMID 35804831, 2022). "Probably as a result of the induction of ICD and proinflammatory IFNγ, the XVir-N-31 injected tumors showed an increased infiltration of activated CD4+ and CD8+ T lymphocytes and a massive reduction in the tumor growth." (PMID 36077380, 2022). "Inosine activation of the A2AR on T cells is itself complex: inosine either prevented Th1 differentiation and blunted anti-tumor immunity in anti-CTLA4-treated mice or, conversely, enhanced both, when co-supplied with IFNγ in vitro and a TLR9 agonist in vivo." (PMID 34986329, 2022). "Mechanistically, IFNγ significantly downregulated the expression of SLC3A2 and SLC7A11, and then impaired the uptake of cystine by tumor cells, which resulted in enhanced lipid peroxidation and ferroptosis." (PMID 36033530, 2022). "For example, cancer immunotherapy has been shown to enhance the effector function of CD8+ T cells, increase IFNγ release to downregulate SLC3A2 and SLC7A11 expression, resulting in reduced cystine uptake and increased ferroptosis in tumor cells." (PMID 34826064, 2022).
tumor (continued). "IFNγ and TNF cooperate to upregulate the expression of p16Ink4a and p21Cip1 to promote tumor cell senescence through the JAK-STAT1 signaling pathways." (PMID 35409271, 2022). "We showed that NK cells in early-stage tumors are a source of IFNγ and that NK depletion reduced HRL expression on tumor vasculature." (PMID 36531040, 2022). "The combination of TLR9 agonists with the PD-1/PD-L1 blockade has shown an elevated number of multifunctional tumor antigen-specific T cells expressing TNF and IFNγ, and a proportion of memory precursor effector cells." (PMID 35745800, 2022). "We found a statistically significant increase in production level of IFNγ in both CD4+ Th (p < 0.02) and CD8+ T-cells (p = 0.0079) in all tumor-bearing mice in comparison with control." (PMID 36555468, 2022). "Nevertheless, in general, IFNγ pathway activation appeared greater in EC than CRC, both across the whole cohorts, and among the majority of MMRp/MSS tumours." (PMID 35262923, 2022). "This observed tumor weight difference translates into functional relevance based on CD4 IFNγ levels, and hence, we categorized the CD4 IFNγ high expression group as responders and the CD4 IFNγ low expression group as non-responders to the ITI-1001 treatment." (PMID 35651802, 2022). "STAT3-/- hosts had increased IFNγ production by CD8+ T cells, tumor infiltration, and decreased number of Tregs." (PMID 35270020, 2022). "The combination of 5-FU with ICB augmented an inflammatory tumor microenvironment with markedly increased CD8+ T cell activation and upregulation of IFNγ, TNFα and IL-1β signaling." (PMID 35634282, 2022). "We found that the IFNγ levels of total, CD4+ and CD8+ T cells in visceral fat increased on day 5, suggesting 5Aza's potential role in enhancing the anti-tumor activity of T cells." (PMID 34976218, 2022). "We assessed the intracellular production of IFNγ by intracellular staining (ICS) and confirmed the significant increase in its expression in both CD4+ Th and CD8+ T-cells in all tumor-bearing mice." (PMID 36555468, 2022). "We further employed immunofluorescent staining to evaluate the spatial relationship between tumor hypoxia and CD8+ T cell infiltration and IFNγ expression in TNBC." (PMID 35840558, 2022). "Cluster 2 expressed a higher level of interferon-gamma (IFN-γ) than did the other CD4+CXCL13+ clusters, indicating that this type of CD4 T cells has a potential role in killing tumor cells." (PMID 36357424, 2022). "Within the TME, mavorixafor alone increased CD8+ T-cell infiltration, granzyme B signal, antigen presentation machinery, and both tumor inflammatory signature (TIS) and IFNγ gene expression signature scores." (PMID 36923305, 2022). "The majority of IFNγ+ cells were CD44+CD62Lneg and were similar per g tumor in isotype and NK depleted mice." (PMID 36531040, 2022). "MIF interacts with its receptor CD74 to activate the IFNγ-JAK-STAT pathway, resulting in significant upregulation of PD-L1 in melanoma cells, which aids in tumor cell escape from the immune response and maintenance of immunosuppressive TME." (PMID 35842634, 2022). "The anti-tumor effects of VTX-2337 plus cetuximab were accompanied by increased splenic lymphoid DCs, IFNγ+ CD4+ and tumor-specific CD8+ T cells." (PMID 36476317, 2022). "Interferon gamma (IFN-γ) is a cytokine secreted by CD4+ T cells, CD8+ T cells and NK cells that plays a major role in tumor cell recognition and destruction through different pathways." (PMID 35625811, 2022). "Piezo1-/- mice had more Foxp3+ Treg cells, fewer IFNγ+ TH1 cells, and normal numbers of TH2, TH17, CD8+T cell, and IFNγ+CD8+T cells in tumor tissue compared with WT control." (PMID 35993548, 2022). "Tumour-induced glucose restriction in the TME reduces NK cell glycolysis and disrupts normal NK cell effector functions, such as interferon-gamma (IFN-γ) production and target cell damage, ultimately suppressing antitumour capacity." (PMID 36578477, 2022).
tumor (continued). "By releasing an extracellular regulator, galectin-3, tumor cells are capable of blocking interferon gamma (IFN-γ) in the TME followed by impeding chemokines CXCL9, CXCL10, and CXCL11 leading to obstructed T-cell recruitment into the tumor bed." (PMID 35053449, 2022). "This mixture was capable of inducing a robust interferon-gamma-producing CD8 T-cell response and improve the therapeutic efficacy of checkpoint inhibitors in syngeneic tumor models, supporting the potential for a “designer mix” therapy." (PMID 35474500, 2022). "In line with this, FACS analysis of expression of IL-2, IFNγ and TNF-α expression in T cells through intracellular staining revealed that combination therapy resulted in increased effector function of tumor-infiltrating CD8 + T cells." (PMID 36457047, 2022). "An increase in GrB+ and IFNγ+TNFα+ CD4+ T cells with fewer central memory T cells and surprisingly fewer IFNγTNFα+ CD8+ T cells in tumor, with a decreased presence of myeloid, notably HLA-DRlo cells, correlated with smaller tumors." (PMID 36419897, 2022). "CD8+ T lymphocytes identify and kill tumor cells playing a role in the anticancer immune response, and are usually supported by CD4+ T helper cells that release interferon-gamma (IFNγ) and interleukin-2 (IL-2)." (PMID 35958590, 2022). "These cells can directly induce tumor apoptosis via granzyme B (CTLs only) and production of IFNγ and TNFα, two cytokines which broadly reprogram the TME and can induce apoptosis in tumor cells." (PMID 35406557, 2022). "Cytokines regulated by NF-κB and STAT3 can either be tumor-inducing (TNF, IL-23, IL-6) or tumor-inhibiting (IFNα, IFNγ, TRAIL)." (PMID 35327456, 2022). "In melanoma and colorectal cancer, vacuolar protein sorting 34 (VPS34) inhibition by SB02024 or SAR405 upregulates the level of CCL5, CXCL10, and IFNγ in the TME, resulting in increased tumor infiltration of NK cells and T cells." (PMID 36230955, 2022). "Besides, the tumor-killing functionality of TAMs should also be ideally achieved through various mechanisms, e.g., the phagocytosis of tumor cells, secretion of cytokines (e.g., IFNγ and TNFα), production of inducible nitric oxide synthase, and induction of anti-tumor inflammation." (PMID 34675914, 2021). "The combination of tumor cell SHP2 knockout with SHP099 treatment exhibited more significant effect on regulation of T cell function and IFNγ signaling." (PMID 33446805, 2021). "During traditional CART therapy, IFNG is the major indicator reflecting the level of CART expansion and cytotoxicity against tumor cells, and significantly elevated IFNG overlaps closely with highly increased IL615." (PMID 34518515, 2021). "The anti-tumor effects of VTX-2337+ cetuximab were accompanied by increased splenic lymphoid DCs and IFNγ+ CD4+ and tumor-specific CD8+ T cells." (PMID 33452311, 2021). "Tumor and splenic lymphoid DCs, CD69+ NK cells and IFNγ+ CD4+ T cells were significantly increased in CTX-treated tumors compared to controls but there was no further increase in VTX+ CTX-treated tumors compared to CTX alone." (PMID 33452311, 2021). "In the tumor microenvironment, IFNγ is secreted by T lymphocytes to reactivate macrophages and CD8+ T cells, but it also stimulates PD-L1 overexpression in tumor cells through the JAKs-STAT1 signaling pathway." (PMID 34685495, 2021). "Of note, we focused on three strongly positively related genes in TCGA and METABRIC datasets, including GZMA, IFNG, and PRF1, which played a crucial role in anti-tumor immune of T lymphocytes." (PMID 33407498, 2021). "We have observed significant upregulation of IFNG, JAK3, STAT1, and STAT2 in tumor compared to normal samples." (PMID 33980865, 2021). "The outcome of combination immunotherapy using anti-VISTA plus anti-PD-L1 or anti-PD-1 antibodies increased TNFα, IFNγ, and serine protease such as granzyme B (GrzB) in CD8+ T lymphocytes and decreased the tumor growth." (PMID 34639059, 2021).